SPRR2A (small proline rich protein 2A)
Description:
Gut bactericidal protein that selectively kills Gram-positive bacteria by binding to negatively charged lipids on bacterial membranes, leading to bacterial membrane permeabilization and disruption. Specifically binds lipids bearing negatively charged headgroups, such as phosphatidic acid, phosphatidylserine (PS), cardiolipin (CL), and phosphatidylinositol phosphates, but not to zwitterionic or neutral lipids. Induced by type-2 cytokines in response to helminth infection and is required to protect against helminth-induced bacterial invasion of intestinal tissue (By similarity). May also be involved in the development of the cornified envelope of squamous epithelia; however, additional evidences are required to confirm this result in vivo.
Tractability: Antibody: UniProt places it where antibodies can reach, with high confidence; its Gene Ontology location is reachable by antibodies, with high confidence.
Gene: Protein-coding gene on chromosome 1 (153,056,120 to 153,057,512, reverse strand). Ensembl gene ENSG00000241794.
Subcellular location: Secreted; Secreted, extracellular space; Cytoplasmic vesicle, secretory vesicle
Pathways (Reactome):
Developmental Biology: Differentiation of Keratinocytes in Interfollicular Epidermis in Mammalian Skin; Formation of the cornified envelope
Gene Ontology:
Molecular function: lipid binding; protein binding
Biological process: antibacterial humoral response; defense response to Gram-positive bacterium; host-mediated modulation of intestinal microbiota composition
Cellular component: cytoplasm; extracellular region; secretory granule; cornified envelope; cytosol; transport vesicle
Genetic constraint (gnomAD): Loss-of-function variants: 4 observed, 2.76 expected, observed/expected ratio (o/e) 1.45, 90% interval 0.63 to 1.93. That is too few expected variants to judge how well the gene tolerates losing a copy. Missense variants: 66 observed, 84.43 expected, observed/expected ratio (o/e) 0.78, 90% interval 0.64 to 0.96. Synonymous variants: 31 observed, 32.95 expected, observed/expected ratio (o/e) 0.94, 90% interval 0.71 to 1.27.
Homologues: Orthologues: chimpanzee SPRR2A (100% identical).
Diseases named in the same sentence as SPRR2A in open-access papers:
SPRR2A is named in the same sentence as 44 diseases in open-access papers, as found by Europe PMC text mining. Sharing a sentence is not in itself a finding about the gene and the disease. The quoted sentences say what the papers report.
psoriasis (5 papers, 2012 to 2025). An autoimmune condition characterized by red, well-delineated plaques with silvery scales that are usually on the extensor surfaces and scalp. "Top up-regulated DEGs in CP vs C include previously identified psoriasis-associated genes such as IL36A/G, SPRR2A/B/F, SERPINB4, S100A7A, S100A9, and IL17F while top down-regulated DEGs include SERTM1, IL6, and ADAMTS16." (PMID 30054515, 2018). "Interestingly, the association of SPRR2A and SPRR2D with psoriasis has been previously confirmed, supporting the relevance of our findings." (PMID 38596682, 2024). "The upregulated OS genes SPRR3 and SPRR2A are the encrypt for the Late Cornified Envelope (LCE) protein present in cornified cell envelope (CE) in both psoriasis and atopic dermatitis; the expression of these genes is linked to keratinocyte terminal differentiation both in vivo and in vitro." (PMID 34925353, 2021). "In addition, genes involved in epidermal differentiation, including IVL, TGM, SPRR2A/B/E/G, SERPINB7/8, are induced in DM (red bar), which have also been shown to be elevated in other inflammatory skin diseases, such as psoriasis and atopic dermatitis." (PMID 22235269, 2012).
gastric cancer (4 papers, 2020 to 2023). A primary or metastatic malignant neoplasm involving the stomach. "Since early diagnosis is very important for treating gastric cancer (GC), we aimed to detect serum small proline-rich protein2A (SPRR2A) to verify its diagnostic value for GC patients." (PMID 32908616, 2020). "While testing the diagnostic efficacy of SPRR2A in gastric cancer, we also tested its biological behavior in cells and found that SPRR2A in gastric cancer cells can promote cell proliferation and migration (data not shown)." (PMID 32908616, 2020). "With regard to other cancers, SPRR2A is upregulated in gastric cancer, but downregulated in cholangiocarcinoma." (PMID 34934042, 2021). "It is worth noting that our results showed that SPRR2A had low specificity between distinguishing gastritis and gastric cancer." (PMID 32908616, 2020). "Unfortunately, the number of specimens in gastric cancer recurrence was limited, so there is no data to show that SPRR2A is a better tumor marker than CEA in gastric cancer recurrence." (PMID 32908616, 2020). "In gastric cancer, serum small proline-rich protein 2A (SPRR2A) is a noninvasive biomarker." (PMID 37664033, 2023). "Since the purpose of selecting gastritis cases was to detect whether the content of SPRR2A was different between gastric cancer and chronic gastritis, we did not select specifically chronic gastritis in our study." (PMID 32908616, 2020).
asthma (3 papers, 2007 to 2021). "The qRT-PCR analysis of these samples verified results for Ccl8 and indicated a down-regulation of 10 other asthma-related genes (Arg1, Ccl11, Ccl24, Ear11, Mcpt1, Sprr2a, Chi3l3, Chi3l4, Chia, Slc7a2) in EOO versus AOO mice." (PMID 18087596, 2007). "While the roles of SPRR1B and SPRR3 in asthma are unclear, it has been shown that the members of the SPRRs family SPRR2A and SPRR2B are upregulated in an IL-13-dependent manner in an allergen-induced asthma model." (PMID 35126350, 2021). "SPRR2A and SPRR2B were found to be increased in ovalbumin and an Aspergillus fumigatus-induced asthma model." (PMID 35126350, 2021). "The exceptions were four variants located on chromosomes 1q21.3 (in/near TCHHL1, HRNR, FLG and SPRR2A) which had significantly stronger effects on age-of-onset of eczema, and one on 17q12 (in GSDMB) which had a stronger effect on the age-of-onset of asthma." (PMID 32603359, 2020).
cholangiocarcinoma (3 papers, 2012 to 2021). A carcinoma that arises from the intrahepatic biliary tree (intrahepatic cholangiocarcinoma) or from the junction, or adjacent to the junction, of the right and left hepatic ducts (hilar cholangiocarcinoma). "In the cholangiocarcinoma and liver cancer model, SPRR2A is activated by STAT-3, promoting EMT through the interaction with ZEB1." (PMID 34934042, 2021). "SPRR2A increases local tumor invasiveness of cholangiocarcinoma." (PMID 33197880, 2020). "Previous data from our group showed that forced expression of SPRR2A in the cholangiocarcinoma cell line SG231, at levels similar to those seen during wound repair responses, induced EMT and significantly reduced cell death under H2O2- and glycochenodeoxycholate-induced cell injury." (PMID 22731250, 2012).
helminth infection (3 papers, 2022 to 2024). "SPRR2A expression is upregulated in response to various helminth infections, including T. spiralis, Nippostrongylus brasiliensis, and H. polygyrus." (PMID 39204209, 2024). "Overall, these findings illustrate that SPRR2A is both influenced by and interacts with the intestinal microbiota and modulates host defence capabilities during helminth infections." (PMID 39204209, 2024). "In addition, type 2 cytokines produced during helminth infection also induce host cells to produce AMPs like small proline-rich protein 2A, which shapes intestinal microbiota composition and protects against helminth-induced bacterial invasion of intestinal tissue." (PMID 36362143, 2022). "A recent study has demonstrated the antimicrobial properties of a unique host-derived bactericidal protein, small proline-rich protein 2A (SPRR2A), in the context of helminth infection." (PMID 39204209, 2024). "Furthermore, H. polygyrus-infected Sprr2a−/− mice harboured a greater bacterial load within intestinal tissue compared to wild-type mice, suggesting a key role for SPRR2A in preventing bacterial invasion during helminth infection." (PMID 39204209, 2024).
gastritis (2 papers, 2020 to 2025). Inflammation of the stomach. "In the present study, serum SPRR2A expression in patients with GC, gastritis, and colorectal cancer and in healthy people was detected by ELISA." (PMID 32908616, 2020). "The median serum SPRR2A concentration in all GC patients was significantly higher than those in healthy controls and gastritis and colorectal cancer patients (P < 0.0001)." (PMID 32908616, 2020). "The median serum SPRR2A concentration in GC patients was significantly higher than those in healthy controls and gastritis or colorectal cancer patients (P < 0.001)." (PMID 32908616, 2020). "The median age of the 100 patients with gastritis was 43 (range 23-70) years, with 58 males and 42 females, and the median absolute serum SPRR2A concentration was 50.07 (30.57-87.54) pg/ml." (PMID 32908616, 2020). "Similarly, the median concentration of SPRR2A was statistically higher in the serum of subjects with gastritis than in healthy subjects." (PMID 40647632, 2025). "Similarly, serum SPRR2A discriminated GC patients from gastritis patients with an AUC of 0.820, with 90.5% sensitivity and 61.7% specificity." (PMID 32908616, 2020). "Similarly, serum SPRR2A discriminated GC patients from gastritis patients with an AUC of 0.820 (95%CI : 0.742–0.899), with 90.5% sensitivity and 61.7% specificity." (PMID 32908616, 2020). "Second, there is no strict restriction on the type of gastritis control cases, and some disease conditions that may affect serum SPRR2A levels, such as infection, ischemia, and diabetes, are not considered." (PMID 32908616, 2020).
inflammatory diseases of the skin (2 papers, 2012 to 2021). "SPRR2A/2D are cornified envelope proteins and known to be involved in inflammatory diseases of the skin." (PMID 34204113, 2021).
lymph node metastases (2 papers, 2020 to 2022). "Then, we assessed the associations between SPRR2A expression and various clinicopathological parameters, including gender, age, tumor size, histological differentiation, Lauren classification, lymph node metastasis, and clinical stage." (PMID 32908616, 2020). "The serum SPRR2A levels in GC patients were associated with lymph node metastasis and the tumor-node-metastasis (TNM) stage (P < 0.05)." (PMID 32908616, 2020). "Significant associations between lymph node metastasis, TNM stage, and serum SPRR2A concentration were observed (P < 0.05)." (PMID 32908616, 2020). "SPRR2A is overexpressed in lymph node metastases, along with an association to non-oropharyngeal location of the primary tumour and is an independent prognostic factor for regional disease recurrence after surgery and radiotherapy." (PMID 35740697, 2022). "The median serum SPRR2A concentrations in patients with lymph node metastasis were significantly higher than those in patients without lymph node metastasis (P = 0.013)." (PMID 32908616, 2020).
acute myeloid leukemia (1 paper, 2022). Acute myeloid leukemia (AML) is a group of neoplasms arising from precursor cells committed to the myeloid cell-line differentiation. "Further, an in-depth literature analysis revealed that several of these genes play important roles in cancer (CDCA3, ECEL1, EN1, HLA-DMB, SPRR2A, TMEM40) including acute myeloid leukemia (CDCA3, HLA-DMB, RPL18A, PF4, PRG3) and T cell acute lymphoblastic leukemia (TLX3)." (PMID 35008420, 2022).
allergic disease (1 paper, 2020). An immune response that occurs following re-exposure to an innocuous antigen, and that requires the presence of existing antibodies against that antigen. "The remaining 3 represent novel associations for allergic disease: rs184587444 in SPRR2A, rs4971089 in KRTCAP2, and rs4809619 in EYA2." (PMID 32603359, 2020).
autoimmune disease (1 paper, 2023). A disorder resulting from loss of function or tissue destruction of an organ or multiple organs, arising from humoral or cellular immune responses of the individual to their own tissue constituents. "NOSTRIN connects to another nitric oxide gene, NOS3, RNF115 to the RAS oncogene family member RAB7A, while SPRR2A connects with EVPL (associated with squamous cell cancer and autoimmune disease)." (PMID 38030619, 2023).
breast carcinoma (1 paper, 2014). "The altered expression of a number of molecular markers, including the progesterone, estrogen, and prolactin receptors, the Na/K/2Cl cotransporter proteins (NKCC1) and aquaporin 5 (AQP5), and several markers of skin differentiation (Sprr2A and keratin 6) has been reported in breast cancer." (PMID 24338153, 2014).
candidiasis (1 paper, 2024). Infection with the organism Candida. "We show that at least 1 family member (SPRR2A) exhibits direct anti-Candida activities in vitro, and SPRRs contribute to control of candidiasis in vivo." (PMID 38949991, 2024).
colorectal cancer (1 paper, 2020). A primary or metastatic malignant neoplasm that affects the colon or rectum. "The expression of serum SPRR2A in patients with colorectal cancer and benign gastritis was also examined." (PMID 32908616, 2020).
COVID-19 (1 paper, 2021). A disease caused by infection with severe acute respiratory syndrome coronavirus 2. "An additional 8 targets (CXCL6, IFI44, IFI44L, RSAD2, S100A8, SPRR2A, SYNE1, XAF1) are associated with COVID-19 pathogenesis, but do not have therapies targeting them available for potential repurposing." (PMID 34582497, 2021).
eczema (1 paper, 2020). "Four of these had a stronger effect on the age-of-onset of eczema: those in/near HRNR (rs1213821), FLG (rs61816761), TCHHL1 (rs115045402), SPRR2A (rs184587444), all within a 1 Mb locus on chromosome 1q21." (PMID 32603359, 2020).
gastric adenocarcinoma (1 paper, 2020). "For the previous study, we found that SPRR2A mRNA in a gene chip is highly expressed in gastric adenocarcinoma." (PMID 32908616, 2020).
gram-positive bacterial infections (1 paper, 2025). Infections caused by bacteria that retain the crystal violet stain (positive) when treated by the gram-staining method. "Studies have found that during Gram-positive bacterial infections, the gut microbiota can induce the production of Small Proline-Rich Protein 2A (SPRR2A), which disrupts the cell membrane of Gram-positive bacteria, preventing such bacteria from breaching the intestinal barrier." (PMID 40357397, 2025).
hepatocellular carcinoma (1 paper, 2021). A malignant tumor that arises from hepatocytes. "We found that the level of SPRR2A transcript was well correlated with that of p73 transcript in both normal liver (Spearman’s r = 0.81) and hepatocellular carcinomas (Pearson’s r = 0.7)." (PMID 34204113, 2021).
Listeria monocytogenes infection (1 paper, 2022). "SPRR2A forms intestinal microflora, limiting bacterial association with intestinal surface and protecting bacteria from Listeria monocytogenes infection." (PMID 36139297, 2022).
prostate carcinoma (1 paper, 2021). A carcinoma that arises from epithelial cells of the prostate gland. "Additionally, we found that the levels of SPRR2A/2D transcripts were correlated with that of p73 in both normal prostate and prostate carcinomas." (PMID 34204113, 2021).
skin aging (1 paper, 2021). The gradual irreversible changes in structure of skin that occur as a result of the passage of time.. "Previously, SPRR2A was already established as a marker for keratinocyte differentiation that responds to skin aging and were thus chosen for this study." (PMID 34339392, 2021).
skin infection (1 paper, 2022). An inflammatory process affecting the skin, caused by bacteria, viruses, parasites, or fungi. "Intravital imaging and quantification revealed that Sprr1a−/−;Sprr2a−/− mice are more susceptible to P. aeruginosa skin infection." (PMID 35234613, 2022). "Sprr1a−/−;Sprr2a−/− mice are more susceptible to MRSA and P. aeruginosa skin infection, revealing that SPRR proteins protect against pathogenic bacterial infections of the skin." (PMID 35234613, 2022). "Thus, Sprr1a−/−;Sprr2a−/− mice are more susceptible to MRSA and P. aeruginosa skin infection." (PMID 35234613, 2022). "Given that SPRR1A and SPRR2A proteins exhibited bactericidal activity against a panel of skin pathogens in vitro, we predicted that the removal of these proteins might promote MRSA and P. aeruginosa skin infection in vivo." (PMID 35234613, 2022).
cancer (11 papers, 2016 to 2025). A tumor composed of atypical neoplastic, often pleomorphic cells that invade other tissues. "Among the identified FRGs, MYBPH, SOST, SPRR2A, and CRNN were notably upregulated in the high-risk group, implying their potential involvement as cancer-promoting genes in BLCA development." (PMID 38172792, 2024). "Although down- and upregulation of SPRR2A were observed in different cancers, higher expression of SPRR2A will increase the local aggressiveness of cancers." (PMID 34934042, 2021). "In contrast, when cancers progress into poor differentiation or lymphatic metastasis, the expression of SPRR2A will decrease to give rise to metastases." (PMID 34934042, 2021). "Additionally, we observed significant expression of CLDN6, CES1, SOST, SPRR2A, MYBPH, CGB5, and KRT1 in the high-risk group, suggesting their potential involvement as cancer-promoting genes in BLCA development." (PMID 37780567, 2023). "Moreover, DSG1, C6orf15, SOST, SPRR2A, SERPINB7, MYBPH, and KRT1 were considerably expressed in the high-risk group, indicating their potential roles as cancer-promoting genes in the development of BLCA." (PMID 37664033, 2023). "Furthermore, the expression of SPRR2A is upregulated first, and then decreases with carcinoma progression (higher stage and lymphatic metastasis) in LUSC and HNSC." (PMID 34934042, 2021). "Thus, we examined whether SPRR2A/2D expression is correlated with p73 expression in normal and cancer tissues." (PMID 34204113, 2021). "We found that the expression of small proline-rich protein 2A (SPRR2A) were negatively regulated by MALAT-1 expression and had an influence on cancer metastasis in vivo." (PMID 27586393, 2016). "It is hypothesised that the levels of SPRR1A and SPRR2A will be altered in the tumour and margin samples from patients with HNSCC, which will reflect their role in the processes of cancer cell proliferation and cancer cell survival." (PMID 40647632, 2025).